FASN (fatty acid synthase)
Diseases named in the same sentence as FASN in open-access papers (continued):
Sharing a sentence is not in itself a finding about the gene and the disease.
Obesity (continued). "Taken together, FASN inhibition alleviated the exacerbation of LPS-induced lung injury under obesity via rescuing lung endothelial dysfunction." (PMID 36922854, 2023). "We examined the expression of FASN in freshly isolated lung endothelial cells to assess the involvement of FASN in obesity-induced ALI exacerbation." (PMID 36922854, 2023). "Taken together, these results suggested that the expression levels of FASN in lung endothelial cells were augmented under obesity during LPS-induced ALI." (PMID 36922854, 2023). "Obesity is a risk factor for CRC and induces the upregulation of lipid metabolic enzymes, such as fatty acid synthase (FASN) and acetyl-coenzyme carboxylase (ACC)." (PMID 35160173, 2022). "Orlistat is an FDA-approved anti-obesity drug that inhibits pancreatic lipase, but it was also found to be a potent inhibitor of FASN via its covalent link to the FASN thiosterase domain." (PMID 36139650, 2022). "Fatty acid synthase is one of the targets of Orlistat, a reversible lipase inhibitor used in the treatment of obesity that works by inhibiting fat-metabolizing enzymes (according to Drugbank)." (PMID 34439872, 2021). "The anti-obesity effect of honey in adipocytes is demonstrated by coumaric and caffeic acids via arresting adipocytes in the G1 phase of cell cycle and inhibiting fatty acid synthase." (PMID 33513715, 2021). "The children who were breastfed showed higher expressions of SLC27A2, FASN, PPARα, and INSR, and were at lower risk to develop obesity." (PMID 34073649, 2021). "This increased expression as result of overweight and obesity was observed even after splitting by sex for FASN and SREBP-1c." (PMID 34526523, 2021). "For example, obesity induced by a high-fat, high-cholesterol diet in mice decreased the expression of hepatic miR-103 and -107, while simultaneously increasing fatty acid synthase protein (FASN), a modulator of fatty acid synthesis." (PMID 33445606, 2021). "CD5L is also known as apoptosis inhibitor 6 (API6) and has been reported to inhibit the activity of fatty acid synthase, in addition to inducing lipolysis during the progression of obesity." (PMID 33808296, 2021). "Another repurposed treatment to combat SARS-CoV-2 is orlistat, an inhibitor of FASN, commonly prescribed for the treatment of obesity and obesity-related T2DM." (PMID 34066434, 2021). "Many FASN inhibitors have been successfully applied for the treatment of other diseases such as obesity, type 2 diabetes, and NAFLD." (PMID 34439559, 2021). "Previous studies in our laboratory have shown that the inhibition of FASN can alleviate obesity in mice." (PMID 32825154, 2020). "In our previous study using diet-induced obesity mice, we confirmed a decrease in the mRNA expression of fatty acid synthase and glucose-6-phosphate dehydrogenase due to a reduction in SREBP-1c mRNA expression." (PMID 33396447, 2020). "Overexpression of FASN plays an important role in tumorigenesis and is thus a vital target of obesity-mediated BC therapy." (PMID 31963198, 2020). "Although Orlistat is a FASN inhibitor that is approved only as an anti-obesity drug, it has also been shown to affect cancer cells." (PMID 33083663, 2020). "The upregulated hsa-miR-7-5p was predicted to target FASN, which is inversely correlated with parameters of glycemic status and its expression is elevated in numerous obesity-related cancers." (PMID 31443156, 2019). "The study aimed to identify fatty acid synthase (FASN), LOC514211, and fat mass and obesity-associated (FTO) gene polymorphisms and to investigate their associations with milk traits in an Indonesian-Holstein dairy cow population." (PMID 31528048, 2019). "FASN is an important enzyme in the de novo lipogenesis pathway and plays a central role in obesity, nonalcoholic fatty liver disease (NAFLD) and cancer cell development." (PMID 30824767, 2019).
Obesity (continued). "Orlistat, a FDA-approved drug for obesity, was reported to bind the thioesterase domain of FASN, which can inhibit tumor growth and induce tumor cell death." (PMID 30824767, 2019). "Inhibition of FASN with the anti‐obesity drug orlistat has been shown to have significant anti‐tumourigenic effects in many cancers, notably breast and prostate." (PMID 29569717, 2018). "Sprague-Dawley rat pups fed with a high-carbohydrate diet exhibited obesity later in life and overexpressed FASN in the liver and adipose tissue." (PMID 30021644, 2018). "Orlistat, an anti‐obesity drug which targets FASN via its thioesterase domain, has shown to possess anti‐proliferative properties and induces apoptosis in tumor cells derived from various malignancies." (PMID 29449326, 2018). "The acute knockout of FASN in adipocytes also protected from high-fat diet-induced obesity and insulin resistance." (PMID 30274245, 2018). "The major hepatic serine hydrolase activities, carboxylesterase 1 (CES1) and fatty acid synthase, were unaltered in human obesity." (PMID 28099843, 2017). "Consistent with its observed anti‐obesity action in older mice, rimonabant markedly decreased mRNA levels of the lipogenic gene fatty acid synthase (FAS) by 4‐fold (P < 0.05) in aged epididymal fat tissue." (PMID 26757949, 2016). "FASn is a key enzyme in fatty acid synthesis, and can significantly increase the deposition of TG in the body and lead to obesity." (PMID 27827939, 2016). "It has been shown that the FASN gene contributes to the regulation of body weight in humans, which results in the development of obesity." (PMID 26290728, 2015). "Low levels of SCD1 and FASN expression are protective against obesity, insulin resistance and NAFLD." (PMID 24473773, 2014). "To determine if HF feeding or obesity also disrupt fatty acid synthase (FAS), another key player in de novo lipogenesis, we estimated FAS levels in mammary glands from LF-fed, HF-Ln, and HF-Ob dams." (PMID 24849657, 2014). "Orlistat is a FDA-approved anti-obesity drug that inhibits the thioesterase domain of FASN, interferes with cellular FA synthesis, can arrest tumor cell proliferation, and induces tumor cell apoptosis." (PMID 22886728, 2013). "MCR1/CD68 ratio increased significantly after weight loss in parallel to adipogenic genes, such as FASN, ADIPOQ, IRS1 and SLC2A4, whereas LEP (an obesity gene marker) and IL6 (an inflammatory marker) decreased." (PMID 23951013, 2013). "We investigated how FASN gene expression in human adipose tissue is related to carbohydrate metabolism dysfunctions and obesity." (PMID 20148112, 2010). "The aim of this work is to investigate how FASN and PPARγ expression in human adipose tissue is related to carbohydrate metabolism dysfunction and obesity." (PMID 20148112, 2010). "We can demonstrate that FASN expression is a good candidate to study the pathophysiology of type II diabetes and obesity in humans." (PMID 20148112, 2010). "There are several studies that connect FASN activity/expression with metabolic alterations in humans such as obesity, dyslipemia, insulin resistance and altered adipocytokine serum profile." (PMID 20148112, 2010). "When the obesity causal genes were overlapped with the fasted and fed networks, 7 genes (ADA, BBS5, CBL, CCND3, FASN, FTO and SCARB1) overlapped with PER1's downstream genes in the fed network (Fisher's Exact Test p-value = 0.037)." (PMID 20168994, 2010). "To prove this idea, we used a fatty acid synthase inhibitor (C75) that was previously designed for obesity control." (PMID 19851456, 2009). "Fatty acid synthase (FASN) is a central regulator of obesity through de novo lipogenesis (DNL), undergoes precise control via the ubiquitin-proteasome system, yet its obesity-related post-translational modifications remain unclear." (PMID 41671397, 2026).
Obesity (continued). "Similarly, lipid metabolism is disrupted using Orlistat, an FDA-approved obesity drug repurposed to inhibit fatty acid synthase (FASN), thereby halting tumor proliferation and inducing apoptosis in PCa models." (PMID 40781676, 2025). "Consequently, inhibitors targeting enzymes such as FASN are currently under preclinical evaluation for cancer therapies, although some drugs targeting these pathways have already been approved for obesity treatment." (PMID 40814339, 2025). "In addition, AIM can also induce anti-obesity effects in fat tissues by combining with fatty acid synthase (FASN) and reducing its activity, promoting lipolysis." (PMID 38178221, 2024). "Orlistat is an FDA-approved anti-obesity drug and its target was identified as FASN." (PMID 38263401, 2024). "FASN is downregulated in patients with obesity but upregulated in patients with normal weight, and the overexpression of FASN is associated with aggressive disease and poor prognosis in several cancer types, including renal cell carcinoma, colon cancer, and prostate cancer." (PMID 38741777, 2024). "Furthermore, in mice models, IL-1β signaling increases hepatic lipogenesis and steatosis by upregulating fatty acid synthase, thus highlighting the link between non-alcoholic fatty liver disease and obesity." (PMID 38257150, 2024). "However, the role of FASN in lung endothelial cells in modulating LPS-induced ALI under obesity remains to be deciphered." (PMID 36922854, 2023). "Taking into account the etiology of obesity, it should be investigated whether chronic hepatic FASN inhibition improves glycemic control in T2D as well as NAFLD." (PMID 37681411, 2023). "Orlistat, a US FDA-approved drug, is used for the treatment of obesity by preventing the absorption of dietary fat and fatty acid synthase to reduce lipid synthesis, which also significantly inhibits the infectivity of the SARS-CoV-2 virus with an EC50 of 0.39 μM in vitro." (PMID 37387168, 2023). "Collectively, these data indicated that, in Mc4r-KO mice — a model of hyperphagic obesity without leptin deficiency in which hepatic DNL is increased to a lesser extent than in ob/ob mice — hepatic FASN deficiency ameliorated both NAFLD and diabetes." (PMID 37681411, 2023). "Furthermore, the expression of fatty acid synthase (FASN) is positively correlated with obesity and related metabolic dysregulation." (PMID 37334370, 2023). "FASN inhibition exerted a protective effect against lung injury in response to LPS in obesity." (PMID 36922854, 2023). "Screening for fatty acid synthase inhibitors from diverse plant polyphenols could be an important area of research in obesity treatment." (PMID 36829976, 2023). "The mechanisms through which polyphenols can inhibit obesity include inhibiting digestive enzymes (mainly alpha-glucosidase, pancreatic lipase, fatty acid synthase, and alpha-amylase), stimulating energy expenditure, suppressing appetite, regulating lipid synthesis, and modulation of gut microbiota." (PMID 36829976, 2023). "Fatty acid synthase (FAS) is a potential target in the treatment of both obesity and cancer." (PMID 35209113, 2022). "Different from our hypothesis, BCAA increased PPAR-γ and PCK1 expression in the high-glucose and high-fat environment and decreased the expression of FASN; this seems to confirm that BCAA has a positive effect on obesity, but an increased risk of T2DM." (PMID 35893906, 2022). "Additionally, there is a significant anti-obesity drug, orlistat, that has a tremendous drug effect on inhibiting fatty acid synthase." (PMID 35164166, 2022). "A recent study reported that TF3 could ameliorate obesity in high-fat diet–induced mice by oral administration for 9 weeks through the signaling pathway of SIRT6/AMPK/SREBP-1/FASN." (PMID 36105184, 2022). "Studies have shown that FASN is a dual target for the treatment of obesity and cancer." (PMID 35566090, 2022).
Obesity (continued). "Thus, inhibition of integral enzymes, such as fatty acid synthase, is a potential therapeutic target for the treatment of obesity." (PMID 34576802, 2021). "Interestingly, the reductions of PLIN1 and FASN expression are individually reported as improving resistance to HG-induced obesity and insulin sensitivity and reducing adipose tissue inflammation." (PMID 33003504, 2020). "Furthermore, the activation of carbohydrate response element binding protein and sterol regulatory element binding protein-1c upregulated glycolytic enzymes and fatty acid synthase to promote hepatic lipogenesis in obesity." (PMID 32508918, 2020). "First, we investigated the cytotoxic potency of 3 inhibitors of FASN, the cerulenin derivative C75, the anti-obesity drug Orlistat, and TVB-3166, one of a series of structurally related FASN inhibitors that includes TVB-2640, the first-in-human FASN for cancer clinical trials." (PMID 33083663, 2020). "Furthermore, obese adipocytes also overexpress metabolic markers such as fatty acid synthase (FASN), which is associated with adipocyte hypertrophy and increased proinflammatory adipocytokine secretion in obesity." (PMID 31963198, 2020). "Similar effects were described in HFD-fed hamsters, where Mulberry water extracts exerted anti-obesity effects by inhibiting lipogenesis (downregulation of fatty acid synthase (FASN) and 3-hydroxy-3-methylglutaryl-coenzyme A (HMG-CoA) reductase) and upregulating PPARα and CPT1A." (PMID 32785059, 2020). "Our laboratory has found that clove extracts can prevent obesity in mice by depressing FASN." (PMID 32825154, 2020). "Besides FASN, orlistat also inhibits (gastric and pancreatic) lipases and for this activity, orlistat is often prescribed as an anti-obesity drug." (PMID 30682837, 2019). "Moreover, fat-specific FASN knockout mice were protected from high-fat diet-induced obesity and exhibited an improvement of glucose tolerance and insulin sensitivity." (PMID 30274245, 2018). "We observed that the addition of cDDGS positively affects the expression of several genes that have been recently proposed as potential targets for the treatment of obesity, diabetes, cardiovascular disease, and Alzheimer’s disease (e.g., FASN, AACS, ALAS1, HMGCS1, and VSIG4)." (PMID 30509175, 2018). "Moreover, we report that when obesity was controlled by using pharmacological or dietary interventions, the levels of FASN, Cav-1, and P-gp were reduced which correlates with improvement in the effectiveness of DTIC on ectopic tumors in mice." (PMID 27980732, 2016). "In another study, aqueous mulberry extract exhibited anti-obesity effects by upregulating hepatic peroxisome proliferator-activated receptor α and carnitine palmitoyltransferase-1 expression, and reducing fatty acid synthase and 3-hydroxy-3-methylglutaryl-coenzyme A (HMG-CoA) reductase expression." (PMID 24137248, 2013). "Obesity may also reduce survival of patients, most likely due to interaction between the fatty acid synthase and adipose tissues." (PMID 23202913, 2012). "The anti-obesity effects of this herb, however, may be attributed to the inhibition of fatty acid synthase, which is shown in the reduction of body fat composition." (PMID 22550541, 2012). "Orlistat is an anti-obesity agent that inhibits lipase/fatty acid synthase activity." (PMID 23029529, 2012). "Likewise, orlistat, a specific inhibitor of FASN currently used in the treatment of obesity, reduced cell proliferation in myeloma cells." (PMID 23029529, 2012). "Taken together, it has been demonstrated that FASN is a candidate gene for the pathophysiology of human obesity and type II diabetes and we corroborate this with the correlation of adipose FASN mRNA expression with several parameters related to obesity and diabetes." (PMID 20148112, 2010). "Moreover, FASN is a variable that plays a role in body weight regulation and the development of obesity." (PMID 20148112, 2010).
Obesity (continued). "Specifically, FASN (EC 2.3.1.85) is a multifunctional enzymatic complex, important in the regulation of body weight and the development of obesity and necessary for de novo synthesis of long-chain saturated FAs from acetyl coenzyme A (CoA), malonyl-CoA and NADPH." (PMID 20148112, 2010). "In this and previous studies, our laboratory has found that FASN relates inversely with obesity and this suggests that it could play a role in obesity-associated diabetes." (PMID 20148112, 2010). "Fatty acid synthase (FASN) catalyzes the conversion of malonyl CoA and acetyl CoA to the saturated C16 fatty acid palmitate, which plays a key role in DNL, making this multi-catalytic protein an attractive therapeutic target for obesity, and associated liver diseases." (PMID 37361533, 2023). "However, under the condition of obesity, whether and how FASN regulates lung inflammatory response during the development of LPS-induced ALI remains elusive." (PMID 36922854, 2023). "Enhanced DNL is a major contributor to hepatic steatosis both in these 2 mouse models of genetic obesity and in obese patients with NAFLD, suggesting that inhibition of DNL by hepatic FASN deficiency may ameliorate hepatic steatosis in a manner dependent on the extent of the enhancement of DNL." (PMID 37681411, 2023). "Besides, obesity and metabolic syndrome were associated with further accumulation of TAG, DAG, and FFA in the cells that stemmed from subADMSCs accompanied by an increase in FASN and DGAT1 protein expression." (PMID 35563741, 2022). "FASN may have a role in body weight regulation and the development of obesity." (PMID 34564583, 2021). "According to these data, higher expressions of SLC27A2, FASN, PPARα, and INSR genes in the children’s blood reflected a protective role of breastfeeding, as these genes are indicators of a lower risk of developing insulin resistance and dyslipidemia linked with obesity in children." (PMID 34073649, 2021). "Consequently, inhibition of the fatty acid synthase by the anti-obesity drug orlistat, the antibiotic FASN inhibitor cerulenin, and the SCD1 inhibitor CAY10566 resulted in decreased CHIKV and MAYV genome replication." (PMID 34372513, 2021). "FASN might also play an important role in the development of obesity-related T2D." (PMID 32709145, 2020). "Importantly, it was estimated that 40-70% of genetic factors that are related to cancer development were found to be strongly associated with obesity, including those involved in lipid metabolism, such as LPIN1, hormone-sensitive lipase LIPE and fatty acid synthase FASN12,38,39." (PMID 33203880, 2020). "In contrast, obesity or consumption of a high-fat diet leads to decreased levels of bilirubin and PPARα, resulting in elevated FAS (fatty acid synthase) and ACC (acetyl-CoA carboxylase) expression, which promotes triglyceride accumulation." (PMID 41425635, 2025). "Previous studies have reported a positive correlation between MEG3 and lipogenic genes, such as FASN and PPARG, in the subcutaneous adipose tissue of females with obesity." (PMID 40806129, 2025). "Long non-coding RNAs, particularly MEG3, are involved in obesity through regulation of lipogenic genes including ATF4, FTO, SREBP1, FASN, and ACACA." (PMID 40806129, 2025). "The mRNA expression of SREBP1 (p = 0.0176), FASN (p = 0.0412), ACACA (p = 0.0255), FTO (p < 0.0001), and ATF4 (p < 0.0001) was significantly reduced in the obesity group compared to the control group." (PMID 40806129, 2025). "Fatty acid synthase (FAS), a key enzyme in lipogenesis, has been identified as a potential therapeutic target for obesity due to its role in adipocyte differentiation and lipid accumulation." (PMID 39201266, 2024). "Accordingly, FASN and SCD1 inhibitors have been subjected to clinical trials with a view to ascertaining their potential utility in the treatment of patients with obesity or MASLD." (PMID 39409049, 2024).